Y_RNA (Y RNA )
Gene: Miscellaneous RNA gene on chromosome 12 (51,156,868 to 51,156,977, reverse strand). Ensembl gene ENSG00000200953.
Homologues: Orthologues: chimpanzee Y_RNA (99% identical), macaque Y_RNA (96% identical). Paralogues in human: RNY1 (88% identical), Y_RNA (85% identical), Y_RNA (84% identical), Y_RNA (83% identical), RNY1P7 (82% identical), Y_RNA (82% identical), Y_RNA (81% identical), Y_RNA (80% identical), RNY1P11 (79% identical), RNY1P8 (79% identical), Y_RNA (79% identical), Y_RNA (78% identical), and 95 more.